TNF (tumor necrosis factor)
Diseases named in the same sentence as TNF in open-access papers (continued):
Sharing a sentence is not in itself a finding about the gene and the disease.
steatosis (continued). "Increased CYP2E1 activity correlates with the degree of steatosis and level of the inflammatory cytokines (e.g., TNF-α) involved in the pathology of NASH." (PMID 25406833, 2014). "Multiple chemokines and cytokines have been implicated in the development of steatosis and the progression to NASH; including IL-6, TNF-α, MCP-1 and IL-10." (PMID 24039859, 2013). "A significant correlation among indexes of fibrosis, body mass index, insulinemia, plasma levels of transforming growth factor-beta, tumor necrosis factor-alpha, degree of steatosis, and gamma-glutamyl transpeptidase was observed." (PMID 22991573, 2012). "Our study shows that TNF-α levels were increased in both the steatosis and resveratrol groups as compared to the control group, suggesting that TNF-α is an important factor in liver damage occurring in NAFLD." (PMID 18782455, 2008). "So, high amounts of FFAs, neurohumoral and pro-inflammatory mediators, particularly TNF-a, which is increased in portal-hypertensive rats, will hit the liver inducing inflammation and steatosis." (PMID 18271959, 2008). "In parallel, sympathetic input enhances the pro-inflammatory state by promoting Kupffer cell cytokine production, particularly tumor necrosis factor-alpha (TNF-α) and interleukin-6 (IL-6), thereby pushing the progression from steatosis to steatohepatitis 173,174." (PMID 41424854, 2026). "Dietary addition with 10% glycerol only increased TNF-α concentration, steatosis, relative abundances of Escherichia_shigella, Lachnospiraceae_XPB1014_group, Coprococcus, Lactococcus and Megamonas, but decreased SLC7A11 expression in liver of growing-finishing pigs." (PMID 40607347, 2025). "Steatosis contributes to elevated levels of the transcription factor–nuclear factor kappa B (NF-κB) and stimulates synthesis of proinflammatory factors such as interleukin (IL)-6 and 1β, and tumor necrosis factor-alpha (TNF-α)." (PMID 40427477, 2025). "Importantly, we have demonstrated here and previously in an ethanol-diet model of steatosis/steatohepatitis that TNFα indeed is crucial for the accumulation of lipid in the liver." (PMID 40766326, 2025). "Results of this study indicated that pigs only supplemented with 0.06% vitamin C and 0.05% niacinamide mixture had higher level of ferrous ion in liver, but had less steatosis and lower concentration of TNF-α in liver compared with pigs offered with 10% glycerol alone." (PMID 40607347, 2025). "The study highlighted the positive effects of flavonoid supplementation (≥500 mg daily) and a significant reduction in ALT (especially for dihydromyricetin), AST (silymarin), GGT (hesperidin), TAGs (genistein), LDL-C (hesperidin and dihydromyricetin), TC, steatosis scores, TNF-α, and NF-κB." (PMID 40141037, 2025). "Interestingly, TNF has been shown to promote steatosis by altering lipid metabolism and inducing fatty acid uptake in the liver, further showing the critical link between inflammation and hyperlipidemia." (PMID 40261813, 2025). "Besides motivating inflammation, the generation of proinflammatory cytokines such as TNF‐α also functioned as a potent lipid metabolism regulator, accelerating hepatocyte lipid deposition and steatosis." (PMID 40501499, 2025). "The role of TNF-α in the transition of steatosis to NASH is widely reviewed in many literatures." (PMID 38884676, 2024). "Considering that macrophages‐derived proinflammatory cytokines (IL‐1β, IL‐6, and TNF‐α) may regulate hepatocyte steatosis and apoptosis, we constructed a coculture system to observe whether a crosstalk exists between these two cell types." (PMID 39279458, 2024). "Furthermore, elevated levels of TNF-α can result in hepatic TG storage and steatosis, which triggers the activation of NF-κB, creating vicious cycles that exacerbates liver injury." (PMID 39238062, 2024).
steatosis (continued). "The type M1 triggers inflammation and fibrosis in MASLD, and one of the most important cytokines from Kupffer cells and monocyte-derived hepatic macrophages that function TNF, which plays a role in steatosis in MASLD degeneration, inflammation and development of fibrosis." (PMID 38917217, 2024). "Steatosis induces the production of pro-inflammatory mediators like TNF-α, IL-6 and IL-1β." (PMID 37705071, 2023). "Now, TNF-α signaling through TLR4 pathway activates multiple intracellular as well as intercellular signaling cascades that lead to progression of liver diseases from steatosis to steatohepatitis, fibrosis and cirrhosis." (PMID 38146363, 2023). "The rise in the circulatory inflammatory cytokines interleukin-1β, interleukin-6 and tumor necrosis factor-α and increase in hepatic stiffness and steatosis in battery factory workers after chronic exposure to lead were reduced following chelation therapy with intravenous CaNa2EDTA." (PMID 37090774, 2023). "TNFα was significantly higher in the simple steatosis patients with respect to control individuals." (PMID 36589452, 2022). "ADMSCs infusion reduced liver weight, steatosis and expression of IL‐6, TNF‐a, and F4/80." (PMID 34985174, 2022). "Our data would suggest that TNFα may be a useful early biomarker for differentiating control participants from patients with early-stage liver disease (simple steatosis)." (PMID 36589452, 2022). "Indeed, the administration of germinated millet flour prevented hepatic inflammation and steatosis in HFD-fed animals by decreasing the hepatic levels of TNF-α and stimulating those of IL-6." (PMID 35565759, 2022). "The results showed that rosavin treatment significantly improved the liver function tests and lipid panel, decreased the hepatic expression of IL-6 and TNF-α proteins, and diminished the percentage and stage of steatosis, inflammation, and fibrosis as compared with the untreated NASH group." (PMID 36077546, 2022). "Indeed, anti-TNF alpha antagonism reversed intestinal inflammation and improved steatosis in rodent models and humans." (PMID 35566749, 2022). "In addition, HLF increased the activities of plasma SOD, CAT, and GSH-Px and decreased the levels of Casp 1, NLRP3, IL-1β, IL-18, and TNF-α, improving the degree of hepatocyte steatosis and inflammatory infiltration of rats." (PMID 36425260, 2022). "Interleukin 6 and TNFα play a central role in the promotion of liver inflammation and steatosis." (PMID 36232372, 2022). "Therefore, miR‐22 can regulate inflammatory effects of steatosis by affecting the expression of the pro‐inflammatory factors TNF‐α and IL‐6." (PMID 33159388, 2021). "Steatosis, entails the activation of the transcription factor nuclear factor kappa B (NF-κB), with the consequent production of pro-inflammatory cytokines such as tumor necrosis factor α (TNF-α), IL6 or IL1β." (PMID 32485811, 2020). "This hydroxycinnamic compound also fibrosis development mediated by pro-inflammatory citokines such as TNF, IL-6 and IL-1β and scavenges ROS production in alcohol consumption, reducing the steatosis, apoptosis and fibrosis development pathways mediated by TNF and TGF-β." (PMID 33203174, 2020). "Steatosis in the WD group was confirmed by the increased level of the tissue triglycerides (TGs) and cholesterol, and mild inflammation by the level of liver tumor necrosis factor alpha (TNF-α) and interleukin 6 (IL-6)." (PMID 32046101, 2020). "To determine whether TNF alone is sufficient to induce steatosis in hepatocytes from ND mice, we treated isolated hepatocytes with various concentrations of TNF, resulting in a dose-dependent increase in LD size and area." (PMID 33050035, 2020). "Furthermore, Quer reduced liver lipid steatosis and inhibited the expression of proinflammatory cytokines, such as tumor necrosis factor-α, IL-6, and IL-1β." (PMID 33076582, 2020).
steatosis (continued). "Additionally, procyanidins exert a protective effect against ALD ameliorating SREBP-1-mediated steatosis and inflammation via IL-6 or TNF, with a possible involvement in preventing mitochondrial dysfunction and apoptosis." (PMID 33203174, 2020). "To determine whether this release of TNF was sufficient to explain the steatosis observed in HFD hepatocytes, we incubated hepatocytes from ND mice with culture supernatants of Kupffer cells either from ND or HFD mice." (PMID 33050035, 2020). "Injured liver cells can release damage-associated molecular patterns (DAMPs) to promote the activation of the NF-κB pathway, thus inducing the production of pro-inflammatory cytokines like TNF-α and ILs, which is a key step in the progression from simple steatosis to NASH." (PMID 31835339, 2019). "Inflammation, steatosis, ballooning, and fibrosis are the features of non-alcoholic fatty liver disease (NAFLD), and the associated critical bona fide genes such as MCP-1, TNF, TNFR1, TGFβ1, Colα1, αSMA, Timp1, and Hp were significantly enriched in the livers of mice fed an HFD." (PMID 31616013, 2019). "Groups that were fed the HF diet showed increase in liver weight, liver fat percentage, and ALT and TNF-α levels, with these liver changes all being characteristic of steatosis, whereas treatment with açai effectively inhibited the increase of these parameters." (PMID 31147590, 2019). "TNF-α can induce the accumulation of TG in the liver, leading to hepatocyte steatosis." (PMID 30405443, 2018). "TNF-α interferes with insulin signaling, thereby favoring steatosis, and may play a pro-inflammatory role in the pathogenesis of NAFLD." (PMID 30110395, 2018). "Therefore, agents that have antioxidant, anti-inflammatory and anti-steatosis properties, particularly anti-TNF production and decreasing lipid accumulation, represent promising therapeutic interventions for alcoholic liver disease." (PMID 27298813, 2016). "Therefore, agents that have antioxidant, anti-inflammatory and anti-steatosis properties, particularly anti-TNF production and decreasing lipid accumulation, represent a promising therapeutic intervention for alcoholic liver disease." (PMID 27298813, 2016). "Steatosis (a primary insult) can sensitize the liver to secondary serious insults including reactive oxygen/nitrogen species, gut-derived endotoxins, pro-inflammatory cytokines like tumor necrosis factor-alpha (TNFα), resulting in NASH development." (PMID 26506376, 2015). "Moreover, adiponectin is largely mediated by an increase in fatty acid oxidation, associated with activation of AMPK and PPAR-α pathways and suppressing hepatic production of TNF-α that appears to protect the liver from steatosis." (PMID 26101535, 2015). "The current study was designed to evaluate the protective effects of SGR against ethanol-induced steatosis and to investigate the effects of ethanol and SGR on the levels of adiponectin, TNF-α, AMPK, PPAR-α, and SREBP-1c for the underlying mechanisms exploration using mice as an experimental model." (PMID 26101535, 2015). "In this study, eotaxin-2/CCL24, IL-1α, IL-12, and TNF-α production in mice treated with CCl4 was increased compared with that in control mice, suggesting these cytokines and chemokines play a critical role in CCl4-induced steatosis." (PMID 25799095, 2015). "TNF-α plays an important role throughout the progression of steatosis to NASH." (PMID 25406833, 2014). "Infliximab, a potent TNF-α neutralizing monoclonal antibody used in the treatment of many chronic inflammatory diseases, improves steatosis and insulin signaling both in genetic and nutritional experimental model of IR, reducing inflammation and increasing hormonal sensitivity." (PMID 24795720, 2014). "Genetic inflammasome deficiency associated with dysbiosis determines increased concentration of bacterial products in the portal blood which may exacerbate steatosis and increase TNF-α expression." (PMID 25479248, 2014).
steatosis (continued). "The dramatic increase of TNF-a is an important function in the progression of steatosis to NASH." (PMID 24188280, 2013). "Similar to unsatisfactory explanation for pathophysiology of nonalcoholic fatty liver disease (NAFLD) encompassing steatosis plus necroinflammation, controversy remains regarding the efficacy of therapeutic strategy targeting oxidative stress and TNF-α in the treatment of NAFLD." (PMID 22319522, 2012). "Upstream targets TNFα and JNK1/2 activate c-Jun and AP1 proteins, resulting in the production of downstream inflammatory factors like IL-6 and IL-1, which are closely associated with cell death in the steatosis liver observed in non-alcoholic fatty liver disease." (PMID 38429802, 2024). "These pathways activate the pro-inflammatory cytokines interleukin 6 (IL-6) and tumor necrosis factor alpha (TNF-α), which function as cytoprotective agents by reducing the expression of molecules associated with cancer and inhibiting the development of liver tumors related to steatosis." (PMID 39595613, 2024). "Furthermore, PC was shown to be a survival agent with the ability to reverse a number of TNF-α-induced reactions that might be involved in necrosis and steatosis." (PMID 38535313, 2024). "FFA-induced steatosis in HepG2 cells is associated with ROS production and consequent lipid peroxidation, which is also strictly related to the decrease in some antioxidant enzymes such as SOD1 and a concomitant increase in proinflammatory mediators including TNF-α." (PMID 36985448, 2023). "Several studies stated that ACT may exert a direct protective effect on hepatocytes and improve steatosis and oxidative stress by inhibiting the nuclear factor kappa B pathway and further reducing the production of tumor necrosis factor-α (TNF-α) and ROS 17-21." (PMID 37781526, 2023). "The dysbiosis of intestinal flora causes acute immune response, and thus, TNF-α is expressed in large amounts, which activates the expression of genes with lipid synthesis function, such as SREBP-1c gene fragment, through sensitization, thus promoting hepatocyte steatosis." (PMID 35936368, 2022). "Additionally, KC-derived TNFα has been confirmed as one of the inducers of HC steatosis." (PMID 36505488, 2022). "Moreover, hepatic injury and steatosis induced by alcohol were alleviated in TNF-α knockout mice." (PMID 32143357, 2020). "Therefore, in the DEX group with higher TNF-α and IL-6 expression levels, this suggests that steatosis may be related to Kupffer cell dysfunction or activation, TGF-β signaling increased in fatty livers with inflammation." (PMID 30424542, 2018). "In addition, CCl4-induced TNF-α synthesis via stimulation of Kupffer cells might contribute to steatosis." (PMID 25799095, 2015). "IL-10 may play a dual role in controlling liver injury via proinflammatory cytokine TNF-α inhibition and ethanol-induced steatosis, leading to potentiating alcoholic liver injury and ameliorating alcoholic liver injury, or via the inhibition of the hepatoprotective cytokine IL-6." (PMID 26508814, 2015). "However, there should be further study to clarify whether the FFA-induced steatosis promotes expression of TNFα mRNA." (PMID 25057104, 2014). "Cytokines, particularly TNF-α, IL-1b and interleukin-6 (IL-6), are involved in the recruitment of circulating macrophages into the liver and the activation of Kupffer and hepatic stellate cells (HSCs), both contributing to the progression from simple steatosis to steatohepatitis." (PMID 25937854, 2014). "This suggests that SS can result from microcirculatory dysfunction due to steatosis, dysfunction of the microvessels, and the effects of vasoactivators (e.g., angiotensin and inducible NO synthase (iNOS)), hormones (e.g., endothelin), and cytokines (e.g., tumor necrosis factor-α)." (PMID 24424317, 2014). "However, TNF-α levels were lower in the resveratrol group than in the steatosis group." (PMID 18782455, 2008).
steatosis (continued). "Common readouts include histological grading of steatosis, serum liver enzymes (ALT, AST), inflammatory cytokines (e.g., TNF-α, IL-6), insulin resistance indices, and gut microbiota profiling via 16S rRNA sequencing or metagenomics." (PMID 41001122, 2025). "dAGEs feeding increased hepatic AGEs and TAGs levels, oxidative stress, steatosis, steatohepatitis (CD43, IL-6, TNF α), and fibrosis (α-SMA, CTGF, collagen I)." (PMID 40141037, 2025). "SIRT1 deficiency triggers the activation of the NF-κB pathway, leading to increased expression of inflammatory factors like IL-1β, IL-6, and TNF-α, accelerating the progression of NAFLD from simple steatosis to steatohepatitis." (PMID 39949396, 2024). "Given that the progression of steatosis is paralleled by upregulation of TNF-α and other inflammatory markers, we measured TNF-α production in the HepG2 cell model." (PMID 38474427, 2024). "As a critical hallmark of NAFLD, immune cells typically increase at the transition from steatosis to NASH, leading to fibrosis through the release of cytokines like IL-6, IL-1β, IL-17, IL-22, TGF-β, and tumor necrosis factor-α (TNF-α)." (PMID 39273539, 2024). "In steatosis and MASH, intrahepatic B cells secrete elevated levels of IL-6 and TNF-α, which promote the activation of CD4 T cells and their differentiation into Th1 cells." (PMID 39372417, 2024). "In steatosis and MASH, intrahepatic B cells secrete elevated levels of IL-6 and TNFα, which promote the activation of CD4 cells and their differentiation into Th1 cells." (PMID 39372417, 2024). "Another study showed that IL-6 only demonstrated an elevation in NASH patients, but TNF-α significantly increased in all NAFLD categories, i.e., simple and moderate steatosis and NASH." (PMID 38535313, 2024). "EV-treated mice showed reduced levels of steatosis, liver damage (AST, ALT), liver triglycerides, total cholesterol, hepatic expression of TNF-α, IL-1, and IL-6, and restored insulin sensitivity." (PMID 39767754, 2024). "In conclusion, it seemed, after review, that most of the mentioned cellular and soluble mediators, with the exception of TNFα, IL-1β, IL-6 and hs-CRP, were more related to inflammation and fibrosis than steatosis itself." (PMID 36768637, 2023). "In L02 cells, PA treatment notably intensified steatosis levels, elevated TRIM59 expression, and enhanced the secretion of tumor necrosis factor alpha (TNF-α), interleukin 6 (IL-6), and interleukin 8 (IL-8)." (PMID 37867509, 2023). "Modulated the expression of specific gene related to lipid synthesis and conversion, CYP4A1, ACC, TNF-α, SOCS2 and CYP7A1; reduced hepatocyte steatosis and liver cell injury." (PMID 36671814, 2023). "For instance, results of clinical studies have shown that as MASLD progresses from simple steatosis to MASH, TNFα levels increase along in blood, liver, and adipose tissue." (PMID 37683301, 2023). "Given that classically activated M1 macrophages showed increased levels of pro-inflammatory cytokines, including interleukin 1-β (IL-1β), tumor necrosis factor α (TNF α), interleukin 6 (IL6), which induce hepatic damage and steatosis." (PMID 35143415, 2022). "Inflammatory biomarkers IL-1β, IL-6, IL-8, IL-10, and TNFα were all significantly elevated in the NAFLD/NASH patients, with respect to control participants and patients with simple steatosis." (PMID 36589452, 2022). "Markedly higher levels of pro-inflammatory cytokines and chemokine, including TNF-α, IL-6, IL-18, and MCP-1 were detected in NASH serum than in those from the Non-steatosis group." (PMID 36209205, 2022). "HFrD has been proven to induce insulin resistance, hepatic steatosis, ballooning degeneration and fibrosis in transgenic (Tg) MUP-uPA mice, and significantly increased the tumor necrosis factor (Tnf), interleukin (Il)-6, Il1β, Ccl2, Ccl5 and Emr1." (PMID 34867414, 2021).